TNF (tumor necrosis factor)
Diseases named in the same sentence as TNF in open-access papers (continued):
Sharing a sentence is not in itself a finding about the gene and the disease.
infection (continued). "While, during infection, platelets diminish TNF-α release by macrophages, platelets also render monocytes towards a CD16-positive phenotype, which is associated with enhanced TNF-α production." (PMID 32244723, 2020). "Furthermore, WT and Trpm2−/− neutrophils showed similar levels of TNF-α and IL-6 under infection with L. monocytogenes." (PMID 32117251, 2020). "Further, to verify whether LD inhibits CD40 expression induced by other DC maturation stimuli, we analyzed the effect of LD infection on tumor necrosis factor alpha (TNFα)-stimulated CD40 expression." (PMID 33370418, 2020). "We infected immortalised wild-type murine bone marrow-derived macrophages (iBMDMs) using a panel of clinical isolates from the Euro-American and Beijing lineages as well as the H37Rv reference strain, followed by immunoblotting and ELISA for IL-1β and TNF at 24 h post-infection." (PMID 32111888, 2020). "Notably, none of these studies used lower infectious doses so it is unclear if TNF-α mediates detrimental lung damage in all infections." (PMID 32974217, 2020). "Many studies on intracellular pathogens have shown that the simultaneous production of IFN-γ, IL-2, and TNF-α by multifunctional CD4+ T cells may correlate with protection from infection." (PMID 33105734, 2020). "TNF is an inflammatory cytokine that is released by macrophages following infection and injury." (PMID 32309522, 2020). "Infection with Mtb in the post-drug relapse phase, however, was associated with pulmonary activation of several pro-inflammatory cytokines and chemokines that have established roles in enhancing HIV replication including IL-1β, IL-6, TNF-α, and CCL-2." (PMID 32373548, 2020). "Notably, percentages of TNF-α+ TC cells increased in the spleen at later timepoints during the infection in a pattern similar to overall TNF-α+ cells." (PMID 32673362, 2020). "C-reactive protein is an acute-phase reactant protein which is synthesized mainly by hepatocytes but also by blood monocytes in response to infection or inflammation upon stimulation by proinflammatory cytokines as interleukin-6 (Il-6) and tumor necrosis factor-α (TNF-α)." (PMID 32307587, 2020). "During infection, the VE cells are activated by the translocation of NF-κB, due to action of parasite trans-sialidase, to the nucleus and the induction pro-inflammatory cytokines such as TNF-α, IL-6, and IL-8." (PMID 33089078, 2020). "However, a noticeably important breakthrough came from the M. abscessus model of infection in zebrafish, which unraveled the importance of cording as mechanism of immune evasion and the role of TNF signaling in controlling infection." (PMID 32850470, 2020). "For IL-1β and TNF-α, we found significantly increased levels in spinal cord tissue in the infected group ten weeks after infection, and daily artesunate treatment, started two weeks after the infection, significantly reduced the levels of IL-1β and TNF-α." (PMID 32230725, 2020). "Piliponsky and co-workers showed that chymase/mMCP-4 may degrade TNF-α during peritoneal bacterial infections to reduce and control the level of the early inflammatory response, at 6 h after the infection." (PMID 32878208, 2020). "Studying fever during the natural history of infection is relevant because it is an important and common response and is generated by a number of mechanisms including increases in the concentrations of the inflammatory cytokines, TNF- α and IL-6." (PMID 33306742, 2020). "Indeed, the regulation of the ‘TNF-mediated signaling pathway’ was enriched at 3, 6 and 12 h post infection." (PMID 33167855, 2020). "During infection, key mammalian innate immune response factors (e.g., interferon gamma, tumor necrosis factor alpha, interleukin 1 [IL-1], and IL-6) have evolved to modulate iron metabolism in order to inhibit overall iron release and thus starve invading pathogens for the molecule." (PMID 32699121, 2020).
infection (continued). "Consistently, the expression of Ifnb, Il6, or Isg56 and the production of IFN-β, IL-6, and TNF were significantly impaired in primary Rnf115−/− MLFs or BMDCs compared to the wild-type counterparts after infection with HSV-1, or transfection with dsDNA ligands or cGAMP." (PMID 33139700, 2020). "Furthermore, EgCME-E-I159V infection significantly increased the expression levels of the genes encoding interferon (IFNβ) and factors related to antibody and inflammatory responses (IL6 and TNFα, respectively) as compared with EgCME-WT infection." (PMID 32346055, 2020). "Following oral infection of pig with T. gondii oocysts, a significant increase in IFN-γ, IL-15, TNF-α, and inductible-NO gene expressions, in lymph nodes draining sites of infection colonic lymph nodes (CLNs), jejunal Peyer’s patches (PPs) and MLNs, was observed at 7 days post-infection." (PMID 33324583, 2020). "Therefore, regulated TNF expression is essential to promote tissue homeostasis and fight infections." (PMID 32528961, 2020). "Moreover, secondary drastic increase of the levels of TNF-α, IL-1β, IL-6, and IL-8, as well as elevated IL-10, was observed at the terminal phase of infection." (PMID 33553280, 2020). "Interestingly, as already outlined in the section above on innate anti-trypanosome responses, infection control in this model was shown to be dependent on the presence of an INFγ/NO/TNF inflammatory environment." (PMID 32218784, 2020). "However, TNF-α concentration in the peritoneal fluid was significantly higher in animals that received the protein administration before the infection, although in the blood, this same group exhibited significantly lower levels of TNF-α." (PMID 33237133, 2020). "The immune response mounted to an ongoing infection may be divided into two components: the proinflammatory cytokines such as TNFα and IL1β; and anti-inflammatory cytokines such as IL11." (PMID 33182721, 2020). "Similarly, infection of macrophages with E. coli K1 also induced the secretion of large amounts of TNF-α and IL-6." (PMID 31893612, 2020). "More specifically, as an immunomodulatory nutrient, glutamine regulate tight junction proteins (occludin, claudin-1, and zona occludens-1), controls chain reactions of cytokines such as TNF-α and IL-17A, and increases local secretory IgA (sIgA) production for preventing infection." (PMID 33143293, 2020). "In addition, treatment of macrophages with 2-DG or the use of glucose-deprived media impaired the production of proinflammatory cytokines, including IL-1β, TNF, and IL-6, after 24 h of infection." (PMID 32385235, 2020). "By comparing the levels of IL-4 and TNF-α in the control and vaccinated groups post-infection, it was found that the vaccines might regulate the Th1 and Th2 responses to perform the leishmanicidal actions." (PMID 32176727, 2020). "Finally, C. psittaci infection induced robust expressions of type Th2 cytokines interleukin (IL)-4 and IL-10, while interferon gamma (IFN-γ) and tumor necrosis factor-α (TNF-α) displayed a significant decrease compared to H9N2 infection alone at 24 hpi." (PMID 32326284, 2020). "Interestingly, mice administered alcohol 6 or 24 h prior to infection exhibited a significant reduction in GM-CSF and TNF- α when alcohol was administered at 6 h, followed by an increase in both cytokines when alcohol was administered 24 h prior to infection." (PMID 31821337, 2019). "However, endotoxin tolerance in mice, which resembles a mirror phenomenon of the generalized Shwartzman reaction, drastically reduces the TNF production of macrophages while strongly activating their bactericidal activity in infection." (PMID 31269748, 2019). "BCG/LPS infection significantly enhanced the protein expression of TNF-α and IL-6, as well as the secretion of NO (P<0.05 or P<0.01), and TTEP administration downregulated these proinflammatory biomarkers in the liver of BCG/LPS-induced mice (P<0.05 or P<0.01)." (PMID 31080480, 2019).
infection (continued). "On the other hand, olmesartan decreases IL-1β and TNF-α and increases IL-10, which could help the parasite establish an infection by decreasing the levels of proinflammatory cytokines." (PMID 31666114, 2019). "Infection promotes liver inflammation by enhancing IL-1β and TNF-α production." (PMID 30800112, 2019). "Both F4+ETEC and ETEC-derived flagellin are known to trigger the fast secretion of pro-inflammatory cytokines by porcine IECs at the early stage of infection, such as TNF-α, prostaglandin E2 (PGE2), IL-6, IL-8 and IL-1α, which are intended to disarm or destroy invading bacteria." (PMID 31221216, 2019). "For instance, depletion of naive target cells (Characteristic 2) can be due to low recruitment of permissive target cells controlled by pro-inflammatory cytokines, high cellular decay amplified by TNFα, high cell infection or phagocytosis regulated by antiviral and immuno-modulatory cytokines." (PMID 30696429, 2019). "After 8 h of infection, supernatants were collected and analyzed for TNFα." (PMID 31921113, 2019). "This innate inflammatory response leads to marked control of viral titers within 3 days of infection (dpi), is generated independently of Type I and II IFN, TNF, and pathogen associated molecular pattern (PAMP) recognition, and is likely driven by resident memory T (TRM) cells." (PMID 31412088, 2019). "However, if Mφs become activated (e.g., through TNF-α or lipopolysaccharide) after 8–24 h of infection, the intracellular bacteria are still capable to replicate extensively." (PMID 31134082, 2019). "However, a sudden decreased in expression level of TNF can be observed after WSSV infection at 24 hpi." (PMID 31875142, 2019). "On the other hand, resident and recruited innate immune cells produce TNF-α and IL-1β at the site of infection, which contribute to host protection and killing mechanisms in Leishmania infection as well as may account to nociception." (PMID 31138231, 2019). "Therefore, using qPCR, we determined the expression of a variety of cytokines with neutrophil chemotactic properties including IL-6, CCL3, CXCL2 and G-CSF, as well as pro-inflammatory cytokines IL-1β and TNF-α at day 3 (105 PFUs) post-infection." (PMID 30787331, 2019). "However, in Unc93b1 mutant, and Tlr13−/− BMDMs production of IL-6 and TNFα upon infection with S. pyogenes ATCC12344 and M49 was almost abrogated at lower MOIs, indicating a non-redundant role of RNA/TLR13 recognition at low bacterial burden." (PMID 30846984, 2019). "Indeed, MCC950 treatment induced significant decreases in IL-6 and TNF-α levels on day 1 post-infection and total protein levels on days 3 post-infection (sublethal dose) and 5 post-infection (sublethal and LD50 doses)." (PMID 30964929, 2019). "While kidney levels of TNF-α, IL-6, and IL-10 were significantly increased on the third day after infection, the levels of IL-1, IL-12p40, and IL-12p70 were significantly reduced on the sixth day after infection in A/J C5−/− mice when compared to A/J C5+/+." (PMID 31687410, 2019). "The results indicate that the use of Bokashi as feed additives resulted in increased concentrations of pro-inflammatory cytokines TNF-α and IL-6, which increase the protective capacity of the colostrum by stimulating cellular immune mechanisms protecting the sow and neonates against infection." (PMID 29305686, 2019). "However, the moderate infection invoked a stronger response from the immune system, as indicated by the higher levels of pro-inflammatory mediators (TNF and IL-6) compared to the mild case." (PMID 31681022, 2019). "After Trichinella infection, VL group showed a significant increase in TNF-α, IL-1, and IL-6 levels in the serum (P < 0.05), and these results indicate that activated immune cells continue to release inflammatory cytokines after an infection." (PMID 31366385, 2019).
infection (continued). "Further studies with larger patients number with a strong evidence level are crucially needed to finalize the answer whether anti-TNF therapy elevates and if yes on what extent the incidence of infection in JIA children." (PMID 30658717, 2019). "Furthermore, a significant increase in the ratio of TNF receptors (TNFR1:TNFR2) in the hippocampus found after the TMEV-DA infection suggests that the microglial production of TNFα is involved in seizure initiation." (PMID 30669615, 2019). "In this model, intra-cisternal inoculation of rabbits with 5 x 104 CFU of M. bovis Ravenel induced progressive subacute meningitis characterized by high CSF leukocytosis, protein influx, and release of TNF-α, with substantial meningeal inflammation by 28 days post-infection." (PMID 32010638, 2019). "However, CD4+ T cell depletion decreased production of IL-2 and IL-10 in early stage infection, decreased production of IL-17 and TNF-α, and abolished IL-3 production in both early and late stage infection." (PMID 31608052, 2019). "Pro-inflammatory factors, such as TNF-α, upregulate the inflammatory response and cause tissue damage, even in the absence of infection." (PMID 30723253, 2019). "Indeed, HTNV-specific CD8+ T-cells are required for efficient viral clearance in mice via production of IFN-γ, TNF-α, and cytotoxicity, and their low frequency leads to a persistent infection, such as seen in the hantavirus reservoir, deer mice." (PMID 30678246, 2019). "However, this appears unlikely, since patients under therapy with anti-TNF and other biological therapies are continuously monitored for clinical signs and parameters of infections." (PMID 30873157, 2019). "Recently, there is growing evidence that CRP plays an important role in inflammatory processes and host responses to infection including the complement pathway, apoptosis, phagocytosis, nitric oxide release, and the production of cytokines, particularly IL-6 and TNF-α." (PMID 31333451, 2019). "In addition, in the livers, IFN-α1, IFN-β, TNF, and IL-1β mRNA and, in the testes, IFN-α1, IFN-β, TNF, IL-1β, and IL-6 mRNA levels increased following infection of Ifnar1−/− mice." (PMID 31511023, 2019). "Westendorp has reported that persons with high levels of tumor necrosis factor alpha (TNFα) and low levels of IL-10 favor a protective role in infection and will have an extended lifespan, thus suggesting that the balance between pro- and anti-inflammatory cytokines influences longevity." (PMID 30881309, 2019). "Indeed, increased expression of IL-1β as well as TNFα and IL-6 has been described following infection from peritoneal exudate cells and spleen cells in mice 24 hrs post-infection." (PMID 31536604, 2019). "In addition, treatment with the ERK1/2 inhibitor decreased NO and TNF-α production, whereas it slightly increased IL-10 production in pasakbumin A-treated Raw264.7 cells during H37Rv infection, similar to the effect observed in cells infected with H37Rv alone." (PMID 30865638, 2019). "Increased susceptibility to this infection correlated with delayed neutrophil recruitment which correlated with lower levels of the chemokines CXCL1/KC/IL-8, CXCL2/MIP-2 and depressed levels of TNF-α, IL-1, IL-6, and IL-17/IL23 in bronchoalveolar lavage fluid." (PMID 31921165, 2019). "Chemokines such CCL3-5, act to recruit other immune cells to the site of infection and proinflammatory cytokines, such as tumor necrosis factor (TNF), interleukin (IL)-1B, and IL-6, act to activate these cells to prepare them to elicit a potent immune response." (PMID 31616434, 2019). "We also noted that one animal (6303) in the EDIII + AL group showed high levels of serum IFN-γ and TNF-α before and throughout day 7 post immunization, indicating a specific immune status potentially due to an unrelated concomitant infection." (PMID 31285858, 2019).
infection (continued). "Notably, evodiamine administration also markedly increased serum production of IFN-γ and TNF-α at 8 h post infection although their levels were unchanged (IFN-γ) or slightly decreased (TNF-α) at 4 h post infection as compared with vehicle treatment." (PMID 30971927, 2019). "Differences in agent design and affinity to TNF-α could also explain the differences in infection rates between patients treated with etanercept or with monoclonal antibodies." (PMID 30941119, 2019). "The infection induces acute peritoneal recruitment of neutrophils and other innate immune cells, and the local and systemic production of proinflammatory cytokines and chemokines (IL-1β, IL-5, IL-6, TNF-α, RANTES, MIP-1β, MCP-1, KC and IL-10)." (PMID 31024025, 2019). "In turn, another recent study in 841 children, including 388 (46%) exposed to anti-TNF-α during pregnancy, showed no elevated risk of infection compared to non-exposed subjects." (PMID 30643992, 2019). "TNF-α is detectable early in the amniotic fluid following bacterial colonisation and stimulates the production of IL-6, IL-8, matrix metalloproteinases and PGE2 during infection-associated PTL." (PMID 31513646, 2019). "Infection triggered similar cytokine storms in both genotypes as illustrated by the equivalent large quantities found in the bloodstream of Ripk1LPC-KO and Ripk1fl/fl mice, such as for TNF-α, IL-6, and CCL2." (PMID 30622241, 2019). "Thus, the low level of IL-10 production as well as the high ratios of IFN-γ/IL-10 and TNF/IL-10 in vaccine groups confirmed again switching to Th1, and this response is probably involved in controlling the infection." (PMID 31014347, 2019). "Experiments have shown that DENV primary infections were less severe in MIF−/− mice, and they exhibited a significant delay in lethality, indicating that reduced proinflammatory cytokine levels (such as TNF-α) are correlated with lower viral loads at the initial phases of infection." (PMID 31466307, 2019). "TNF-α, IL-1β, and IL-6 are pro-inflammatory cytokines and early inflammatory markers of the body produced by LPS-induced macrophages, which can be secreted and released in large quantities under conditions of injury, infection and immune response." (PMID 31835323, 2019). "Therefore, we evaluated the expression of NF-κB, TNF-α, IL-8 and IL-4 in CEFs following: (i) infection with GaHV-2, (ii) exposure to PFOS, and (iii) combination of both (exposure to PFOS followed by infection with GaHV-2)." (PMID 31238913, 2019). "Interestingly, tmTNF-α pAb markedly reduced bacterial load in blood and peritoneal lavage fluid (PLF) at 24 h after the CLP operation, reserving the anti-infection effect of TNF-α." (PMID 31383857, 2019). "Thus, during clearance of infection, the concomitant increase in IL-4 protects and maintains goblet cell function against the increasing levels of TNF-α and IFN-γ." (PMID 30665337, 2019). "Further studies with strong evidence and longer monitoring period are called for examine the pathogens involved in the infections, the precise severity of the infectious diseases and the localizations as well as to compare the different kinds of TNF-alpha inhibitor drugs." (PMID 30658717, 2019). "The high levels of TNF and the decreased ability of IL-10 to down regulate cytokine production leads to an exacerbation of the inflammatory reaction and development of cutaneous and mucosal leishmaniasis following infection with L. braziliensis." (PMID 31119102, 2019). "It is broadly accepted that IL-12 and TNF-α both are essential for host resistance against infection but overproduction of these cytokines may contribute towards immunopathology." (PMID 31801478, 2019). "Several reports have shown that IFN-γ and tumor necrosis factor alpha (TNF-α) that could evoke cellular immune responses were indispensable to prevent lethal infection in F. tularensis." (PMID 31235714, 2019).